RN7SKP182 (RN7SK pseudogene 182)
Gene: Miscellaneous RNA gene on chromosome 18 (39,016,047 to 39,016,344, reverse strand). Ensembl gene ENSG00000222704.
Homologues: Orthologues: chimpanzee 7SK (85% identical), mouse Gm55615 (53% identical). Paralogues in human: RN7SKP71 (72% identical), 7SK (71% identical), RN7SKP176 (71% identical), RN7SKP189 (71% identical), RN7SKP124 (70% identical), RN7SKP255 (70% identical), RN7SKP78 (70% identical), RN7SKP102 (70% identical), RN7SKP180 (70% identical), RN7SKP48 (70% identical), RN7SKP204 (70% identical), RN7SKP79 (69% identical), and 283 more.